INS (insulin)
Diseases named in the same sentence as INS in open-access papers (continued):
Sharing a sentence is not in itself a finding about the gene and the disease.
type 1 diabetes (continued). "The hallmark of type 1 diabetes is diminutive insulin secretion that subsequently ensued in chronic hyperglycemia." (PMID 27575603, 2016). "Type 1 diabetes is an autoimmune disease characterized by the complete loss of insulin (INS) due to the destruction of β cells, and its treatment is solely dependent on INS administration." (PMID 27786288, 2016). "From a patho-physiological point of view it is understandable that insulin is vital in the case of absolute insulin deficiency, such as type 1 diabetes." (PMID 27391319, 2016). "Diabetes type 1 is caused by genetic factors, such as shortage of insulin and decreased ability to use insulin, a hormone that allows glucose (sugar) to enter cells and be converted to energy." (PMID 27004122, 2016). "Type-1 diabetes (T1D), a major and difficult-to-manage health problem, results from dysfunctional and/or insufficient pancreatic β cells, leading to a loss of insulin as well as glucose homeostasis as the disease advances." (PMID 27983594, 2016). "Of those assigned "probable” type 1 diabetes status, 61% (22/36) had a definite C10E (type 1 specific) diagnostic code and 56% were on insulin exclusively (20/36)." (PMID 27631769, 2016). "Pathological ketoacidosis on the other hand is a medical emergency arising in type 1 diabetes because of acute severe insulin deficiency due usually to interruption of insulin injection." (PMID 27458340, 2016). "We did not have sufficiently detailed data to evaluate associations between type 1 diabetes and cancer incidence according to specific types of insulin." (PMID 26924393, 2016). "The high levels of glucagon in type 1 diabetes and the low levels of insulin are probably an important cause for the elevated levels of glutaminase in this disease." (PMID 27490892, 2016). "Type 1 diabetes (T1DM) is an autoimmune disease characterized by β-cell destruction in the pancreatic islets resulting in the complete loss of insulin secretion." (PMID 27025211, 2016). "Type 1 diabetes (T1D) is a complex disease, caused by the autoimmune destruction of the insulin producing pancreatic beta cells, resulting in the body’s inability to produce insulin." (PMID 27257970, 2016). "Type 1 diabetes is associated with the loss of self-tolerance to the insulin-producing β-cells in the pancreas." (PMID 26975663, 2016). "Type 1 diabetes is associated with substantial morbidity and mortality despite replacement therapy with exogenous insulin." (PMID 26973647, 2016). "In conclusion, we have shown that CSII (insulin pump) use is associated with lower rates of early microvascular complications in a clinic population with type 1 diabetes." (PMID 27050468, 2016). "Recommended therapy for type 1 diabetes by international associations consists of initiation and management of insulin therapy with insulin analogs to achieve desired glycemic goals." (PMID 27119007, 2016). "Type 1 Diabetes Mellitus (T1DM) is caused by an autoimmune destruction of insulin-producing β cells, resulting in chronic hyperglycemia." (PMID 26856418, 2016). "Type 1 diabetes (T1D) afflicts millions of people worldwide and is a severe chronic autoimmune disease characterized by the progressive loss of self-tolerance to insulin-producing pancreatic β-cells." (PMID 26975663, 2016). "Type 1 diabetes is triggered by insulin deficiency, whereas, in most cases, type 2 diabetes is caused by insulin resistance along with insufficient insulin secretion." (PMID 27579308, 2016). "Induction of Type-I diabetes was associated with increased blood glycated hemoglobin level, decreased serum insulin level, decreased body weight and increased mortality rate." (PMID 27790139, 2016). "Obese individuals used lower insulin doses than lean ones, suggesting either suboptimal insulin treatment or clinical heterogeneity of type 1 diabetes, in which higher weight is possibly associated to higher residual beta-cell function." (PMID 27011769, 2016).
type 1 diabetes (continued). "Type 1 diabetes is an autoimmune disease leading to the loss of insulin secretion from the pancreatic β-cells, which ultimately results in high circulating plasma glucose levels and clinical symptoms." (PMID 26620391, 2016). "Hypothyroidism in children with type 1 diabetes is frequently associated with hypoglycemia resulting from increased insulin sensitivity." (PMID 27525273, 2016). "Type 1 diabetes is an autoimmune inflammatory disease that is caused by immune cell mediated destruction of the insulin-producing beta cells in the pancreas." (PMID 26783747, 2016). "Type 1 diabetes is caused by the selective destruction of pancreatic insulin-producing beta-cells by an immune-mediated reaction, predominantly mediated by autoreactive T cells." (PMID 26983628, 2016). "Type 1 diabetes is insulin dependent condition, characterized by deficiency of insulin due to destruction of insulin-producing beta cells of islets of Langerhans by autoimmune system in pancreas." (PMID 26498972, 2015). "Type 1 diabetes is caused by a person's immune system attacking the cells in their pancreas that produce insulin." (PMID 26061776, 2015). "Autoantibodies against antigens expressed by insulin-producing β cells are circulating in both healthy individuals and patients at risk of developing Type 1 diabetes." (PMID 29167731, 2015). "Intensive insulin therapy with continuous subcutaneous insulin infusion (CSII) devices or multiple daily injections (MDI) reduces the risk of long-term vascular complications of type I diabetes (TID)." (PMID 25873144, 2015). "Among patients who are likely to have type 1 diabetes, more careful insulin dose titration is necessary due to the high risk of hypoglycemia." (PMID 25621692, 2015). "STZ-mediated type 1 diabetes is caused primarily by the selective destruction of insulin-secreting β-cells with excessive release of NO production, and its consequence elevated blood glucose in the body." (PMID 25793188, 2015). "Type 1 diabetes (T1D) is an autoimmune disease resulting in the targeted destruction of pancreatic β-cells and permanent loss of insulin production." (PMID 25915398, 2015). "In the present study, we used low dose STZ injection for multiple times to induce the experimental diabetic model, which mimics the type 1 diabetes characterized by absolute deficiency of endogenous insulin secreting." (PMID 26060502, 2015). "In type 1 diabetes, self-proteins, like insulin, become more strongly immunosuppressive when linked to CTB." (PMID 26378585, 2015). "Type-1 diabetes is an autoimmune disease that leads to loss of insulin-producing β-cells in the pancreas, which is often modeled in animal studies with injections of streptozotocin (STZ)." (PMID 26035391, 2015). "Hypoglycaemia is the most common side effect of insulin treatment, with severe hypoglycaemia affecting approximately 25% of patients with type 1 diabetes, and is associated with increased morbidity and mortality." (PMID 25810037, 2015). "Canine diabetes, similar to human type 1 diabetes, is frequently associated with diabetic ketoacidosis at onset or after insulin omission." (PMID 26057531, 2015). "Given RAB5B’s association with type 1 diabetes it is possible that genes in this locus play a regulatory role via that impacts beta cell function or insulin secretion, a process that is impaired in both disorders." (PMID 26305227, 2015). "Type 1 diabetes is caused when an excessive immune response selectively destroys insulin-producing β-cells." (PMID 25793188, 2015). "Type I diabetes, also known as diabetes mellitus, is a common disease characterized by hyperglycemia resulting from a deficiency in insulin production." (PMID 24466155, 2014). "The American Diabetes Association recommends the use of insulin analogs in many patients with type 1 diabetes, particularly those in whom hypoglycemia has been a complicating factor." (PMID 24653838, 2014).
type 1 diabetes (continued). "Patients with type 1 diabetes can achieve strict glycemic control using intensive insulin therapy, but such treatment is associated with a risk of severe or fatal hypoglycemia (low blood sugar)." (PMID 25289645, 2014). "Strict metabolic control can be achieved by intensive insulin therapy in patients with type 1 diabetes, which is associated with the risk of severe hypoglycemia." (PMID 25289645, 2014). "Vitamin B3 has been shown to stimulate β-cell regeneration in partially pancreatectomized rats, lengthen the “honeymoon” period in type 1 diabetic patients, and improve insulin secretion from patients at high risk of developing type 1 diabetes." (PMID 25160946, 2014). "Type 1 diabetes (T1D) results from the destruction of pancreatic insulin-producing beta cells and is strongly associated with the presence of islet autoantibodies." (PMID 25047039, 2014). "This treatment was associated with a gradual disappearance of anti-insulin antibodies and her underlying type 1 diabetes has subsequently been successfully managed with an insulin pump." (PMID 24711924, 2014). "Type 1 diabetes (T1D) is due to a deficiency in endogenous insulin secretion secondary to destruction of insulin-producing beta cells in the pancreas." (PMID 25226393, 2014). "Further in vivo studies to assess the long-term relevance of taurine to the glucagon secretion and glycemic control in insulin-deficient type 1 diabetes are needed to investigate the clinical implications of our findings." (PMID 25393115, 2014). "Insulin is an important autoantigen in type 1 diabetes (T1D) autoimmunity, most likely the primary causative antigen in the spontaneously diabetic NOD mouse, and a target autoantigen in Caucasian individuals with the highest HLA-DRB1*04, DQ8 risk-haplotype." (PMID 24844227, 2014). "Type 1 diabetes is an autoimmune disease caused by the immune-mediated destruction of insulin-producing pancreatic β cells." (PMID 24629100, 2014). "Type 1 diabetes (T1DM) is caused by insufficient insulin secretion due to autoimmune destruction of β-cells." (PMID 25421245, 2014). "Abdominal obesity, type 1 diabetes, hypertension and insulin use were significantly associated with higher odds of DPN." (PMID 25184511, 2014). "Type-1 diabetes (T1D) is a chronic disease caused by the autoimmune destruction of insulin-producing pancreatic β-cells." (PMID 24142387, 2014). "Despite these limitations, the present study is the largest to date which evaluates weight loss, glycemic control, and short-term changes in insulin requirements in patients with type 1 diabetes following GB." (PMID 24668543, 2014). "To further characterise this association, we divided patients with type 1 diabetes into tertiles based on their daily insulin dose." (PMID 24959195, 2014). "Type 1 diabetes (T1D) is an autoimmune disease where T-cell mediated destruction of insulin-secreting β cells causes insulin deficiency and leads to an increased level of glucose in blood and urine." (PMID 25566322, 2014). "Insulin deprivation (type 1 diabetes) results in a fast and marked loss of adipose tissue mass that can be rapidly restored by insulin supplementation, resulting in hypertrophia and hyperplasia of white adipose tissue (WAT)." (PMID 25170835, 2014). "Type 1 diabetes is characterized by deficient insulin production and requires daily administration of insulin." (PMID 24563867, 2014). "Streptozotocin is a cytotoxic glucose analogue, which modifies biological molecules, fragments DNA, and destroys the beta cells, causing a state of insulin-dependent diabetes by deprivation of insulin." (PMID 24563867, 2014). "The addition of metformin to insulin therapy in type 1 diabetes is also associated with reductions in insulin-dose requirement and HbA1c levels." (PMID 23415113, 2013). "T cell-mediated destruction of insulin producing pancreatic β-cells is the hallmark of type I diabetes, an autoimmune disease associated with various genetic and environmental factors." (PMID 23383295, 2013).
type 1 diabetes (continued). "To compare the effects of such diet-induced metabolic perturbations with the effects in an insulin-deficient diabetic condition, we used a type 1 diabetes model by treating C57BL/6 mice with STZ." (PMID 23691124, 2013). "Type 1 diabetes (known as insulin-dependent diabetes or juvenile-onset diabetes) which is caused by a complete deficiency of insulin secretion resulting from a cellular-mediated autoimmune destruction of the β cells of the pancreas." (PMID 23587270, 2013). "Glutamic acid decarboxylase 65 (GAD65), insulinoma-associated protein 2 (IA2), and (pro)insulin appear to be highly antigenic in humans both for T cells and B cells during the natural history of type 1 diabetes." (PMID 23970924, 2013). "Type 1 Diabetes Mellitus (T1DM) is caused by an autoimmune reaction leading to the loss of insulin-producing β-cells resulting in chronic hyperglycemia." (PMID 24204325, 2013). "Uncomplicated pregnancy is an insulin resistant state, and gestational diabetes and Type 1 diabetes increase preeclampsia risk." (PMID 23573260, 2013). "Type 1 diabetes mellitus (T1DM) is caused by the destruction of insulin-producing β cells in the pancreas and is usually the result of an autoimmune disease." (PMID 23662138, 2013). "Patients with type 1 diabetes need to take insulin injections for life and, in order to reduce their risk of developing complications, must ensure their blood glucose levels are sufficient to balance their insulin doses, diet, and activity." (PMID 25100684, 2013). "Type 1 diabetes (T1D) is a chronic disease manifested by the loss of functional insulin producing β cells of pancreatic islets, caused by islet infiltrating self-reactive CD4+ and CD8+ T cells that mediate β-cell destruction." (PMID 23691523, 2013). "Current modifiable risk factors for microvascular complications in type 1 diabetes are recognised to be glycaemic control, blood pressure, lipids, insulin resistance and smoking." (PMID 24083407, 2013). "PUMA methods identified novel susceptibility loci for type 1 diabetes involved in pancreatic function, insulin pathways and immune cell function and for Crohn's disease that are involved in pro- and anti-inflammatory pathways." (PMID 23825936, 2013). "Clinical trials in adults with Type 1 diabetes have shown that insulin detemir is associated with comparable HbA1c, less variability in fasting plasma glucose, less nocturnal hypoglycaemia and less weight gain compared with intermediate-acting NPH 15–18." (PMID 23094597, 2013). "A few years later it was pointed out that Type 1 diabetes (T1D; caused by autoimmune destruction of the insulin-secreting β cells in the pancreas) is increasing at the same rate, and in the same countries (mostly high income) as the allergic disorders." (PMID 24481186, 2013). "A strong association between lipoatrophy and lipohypertrophy with insulin antibodies in children and adolescents with type 1 diabetes has been reported." (PMID 24386337, 2013). "Type I diabetes is characterized by the inability of the body to produce insulin; this is caused by cellular-mediated programming of the autoimmune system and subsequent destruction of pancreatic beta-cells, the cells responsible for insulin production." (PMID 22462028, 2012). "Acute intensive insulin therapy causes a transient worsening of diabetic retinopathy in type 1 diabetes patients and is related to VEGF expression." (PMID 23144758, 2012). "A long-standing goal of immunology is to develop targeted immune therapies that eliminate the predominant cause of type 1 diabetes: the autoimmune T lymphocytes (T cells) that destroy the insulin-secreting cells of the pancreas." (PMID 22905105, 2012). "The fundamental pathology of type 1 diabetes is autoimmune-mediated beta cell destruction, which results in an absolute deficiency of insulin, with only about 1% of beta cell mass remaining in individuals with lifelong type 1 diabetes at autopsy." (PMID 22460761, 2012).
type 1 diabetes (continued). "Type I diabetes (T1D) is a chronic autoimmune disease caused by the specificdestruction of pancreatic β-cells, which produce insulin, Multiple complications are usually associatedwith diabetes mellitus." (PMID 22708778, 2012). "This is in contrast with a recent study demonstrating that a high cumulative dose of insulin associates with an increase in cIMT in type 1 diabetes." (PMID 23185996, 2012). "An early intensification of insulin treatment was associated with about 5-fold reduction of cataract risk in children and adolescents with type 1 diabetes." (PMID 22407349, 2012). "In humans at risk of developing type 1 diabetes, β-cell dysfunction is characterized by hyper-production of insulin." (PMID 23285123, 2012). "Type 1 diabetes (T1D) involves T cell-mediated attack on β-islet cells in the pancreas resulting in a loss of insulin production." (PMID 23028856, 2012). "Since insulin secretion is deficient in STZ-induced type 1 diabetic mice, it is also a good model for research on insulin-independent antidiabetic mechanisms of the compounds." (PMID 22778782, 2012). "Type 1 diabetes mellitus (T1DM) is a chronic autoimmune disease caused by deficiency in insulin secretion." (PMID 23261861, 2012). "Loss of insulin production in type 1 diabetes (T1D) following autoimmune destruction of β cells in the islets of the pancreas requires life-long treatment with insulin injections." (PMID 23152835, 2012). "Type 1 diabetes is a disorder of glucose metabolism that results from insulin deficiency secondary to autoimmune destruction of insulin-secreting β-cells." (PMID 23039762, 2012). "Acute intensive insulin therapy causes a transient worsening of diabetic retinopathy with neovascularization in type 1 diabetes patients and is related to VEGF expression." (PMID 23144758, 2012). "None of these showed any significant evidence of association – including the lead signals from the WTCCC type 1 diabetes study in the HLA region (rs3129941, P = 0.08), or near the INS (rs3842748, P = 0.64) or PTPN22 (rs2476601, P = 0.38) genes." (PMID 22693455, 2012). "Keeping in mind the challenges associated with modelling a chronic disease such as type 1 diabetes the methods of health economic evaluation are highly developed in this field of comparing different strategies of insulin therapy." (PMID 21978524, 2011). "Insulin deficient type 1 diabetes exhibits hyperphagia and is associated with increased expression of NPY in ARC." (PMID 22081645, 2011). "Akita mice have a mutation in the insulin gene and develop the pathological characteristics of type 1 diabetes, including diabetic nephropathy and elevated anxiety symptoms." (PMID 21738623, 2011). "Type I diabetes is a disease that destroys β cells resulting in insulin deficiency, and patients with type I diabetes depend on the administration of insulin for survival." (PMID 22145030, 2011). "Type I diabetes, often called juvenile diabetes, results from the loss of active insulin-producing pancreatic-beta cells which causes an insulin deficit." (PMID 23724283, 2011). "Type 1 diabetes (T1D) is a T-cell-mediated autoimmune disease that involves the progressive destruction of pancreatic β cells resulting in complete loss of insulin secretion." (PMID 22046502, 2011). "We describe two adolescent girls with newly diagnosed type 1 diabetes, who presented with oedema of the lower extremities approximately one week after the initiation of insulin treatment; other causes of oedema were excluded." (PMID 21274337, 2010). "Type 1 diabetes (T1D) results from the progressive destruction of insulin-producing beta cells in pancreatic islets caused by pro-inflammatory and pro-apoptotic effectors of innate and adaptive immunity." (PMID 20949090, 2010). "Type 1 diabetes, caused by the autoimmune destruction of pancreatic β-cells, is deficient in insulin and requires exogenous insulin for treatment." (PMID 20624296, 2010).